IFITM3 (interferon induced transmembrane protein 3)
Diseases named in the same sentence as IFITM3 in open-access papers (continued):
Sharing a sentence is not in itself a finding about the gene and the disease.
infection (continued). "We infected WT and Ifitm3−/− mice with doses of 1, 10, or 50 TCID50 of H5N1 avian influenza virus and measured lung viral loads at day 3 post-infection." (PMID 39477971, 2024). "We used the rescued strain rSczy3 to infect CEKs and performed qRT-PCR to evaluate the relative expression levels of CTSL, CTSB, Abl1, Abl2, IFITM3, ADAM17, TMPRSS2, NRP1, and CD74 at 12 and 24 h post-infection." (PMID 37376546, 2023). "Our results showed that overexpression of IFITM1, IFITM2, IFITM3, or LY6E significantly inhibited the infection of CCoV-HuPn-2018pp and HCoV-229Epp." (PMID 37676001, 2023). "In this study, we proposed an intriguing antiviral mechanism, where LSD1 activates IFITM3 via demethylation, leading endocytosed HCV virions to degradation and infection to failure." (PMID 37947646, 2023). "For ST1, inhibition of infection by IFITM1, IFITM2 and the IFITM3 43AS mutant, which shows broader subcellular localization than IFITM3, was significant." (PMID 36851478, 2023). "While IFITM3 inhibits influenza A virus infection more efficiently than IFITM1, the latter more effectively blocks infection by Ebola (EBOV) and Marburg (MARV) viruses." (PMID 35631059, 2022). "In the present study, IFITM3 was identified as a novel NTCP co-factor that has a significant effect on the HBV and HDV entry and infection process in NTCP-expressing hepatoma cells as well as PHHs." (PMID 35458456, 2022). "IFITM3, which was upregulated in PTC, plays a critical role in actively preventing infection by inhibiting viral-cell fusion." (PMID 35013427, 2022). "Some of the transcripts related to infection by virus that were decreased include TRIM22, NOD2, IFITM3, and SPHK1." (PMID 36059515, 2022). "Our data indicate that, at least in HepG2 cells, in vitro infection with the HDV-1T strain proceeds in an IFITM3-independent manner, whereas infection rates with the HDV-WHO strain were reduced in the HepG2-NTCP and HuH7-NTCP cells under IFITM3 knockdown." (PMID 35458456, 2022). "We previously found that IFITM3 inhibited vaccinia virus and thrombocytopenia syndrome virus (SFTSV) infection." (PMID 35401515, 2022). "While there is clear evidence for a direct PPI between IFITM3 and NTCP, the specific mechanism by which this PPI facilitates the infection process remains to be identified in future studies." (PMID 35458456, 2022). "The antiviral activity of interferon-induced transmembrane protein 3 (IFITM3) on PEDV and TGEV infection was also evaluated." (PMID 35401515, 2022). "In contrast, HuH7-NTCP cells showed significantly lower infection rates in all assays with HBV and HDV after IFITM3 knockdown." (PMID 35458456, 2022). "To test the link between infection enhancement and downmodulation of IFITM proteins by rapalogs, we probed for levels of IFITM3, IFITM2, and IFITM1 by immunoblotting whole cell lysates using specific antibodies." (PMID 33880473, 2022). "Ectopic expression of IFITM2 inhibited infection and partially restored sensitivity to temsirolimus, while the combination of IFITM2 and IFITM3 restricted infection further and fully restored temsirolimus sensitivity." (PMID 33880473, 2022). "This analysis identified a signature for 4 genes, CEBPD (0.93 log2FC), MAFB (0.83 log2FC), IFITM3 (0.55 log2FC), and LGALS1 (−0.53 log2FC), that was markedly enriched in CD14 monocytes in patients who ultimately survived infection." (PMID 35169146, 2022). "Based on the known role of IFITM3 as the virus restriction factor, we aimed to clarify its role for HBV/HDV entry and infection." (PMID 35458456, 2022). "Pre-treatment with AmphoB rescued the entry and fusion of arenavirus GPpp and live MOPV infection in cells expressing either ZMPSTE24 alone or co-expressing ZMPSTE24 and IFITM3." (PMID 35283811, 2022). "Analysis of the IFN-stimulated genes (ISGs) Ifitm3, Irf7, Isg15, and Oas1a at 12, 24, and 72 hpi demonstrated a consistent trend for increased expression following ZIKVCDN infection." (PMID 34193875, 2021).
infection (continued). "In the IFITM3 knockout mouse model, IFITM3 has been reported to inhibit RSV cell infection and control the pathogenesis of the disease." (PMID 33419394, 2021). "While IAV-LP infection was reduced in HFF, MLV-LP infection was enhanced by overexpression of all IFITMs, significantly for IFITM2 and IFITM3." (PMID 34933450, 2021). "The upregulation of IFITM3, STAT1, STAT2, PLSCR1, and NMI after infection was validated using western blotting and qRT-PCR." (PMID 34818332, 2021). "Further study showed that PRRSV particles are transported into endosomes and then into lysosomes during the early stages of infection, and confocal microscopy results revealed that PRRSV particles are transported to IFITM3-positive cellular vesicles." (PMID 32999030, 2020). "The same study confirms an even greater enhancement of SARS-CoV-2 in bypassing IFITM3 defense via TMPRSS2 activation of plasma membrane fusion, and reports compatibility with HCoV-OC43 mode of enhanced infection." (PMID 33240681, 2020). "Viral titers were reduced by very similar amounts in control cells (380-fold) compared to IFITM3 knock-out cells (300- and 360-fold) for MR766 infection and in control cells (680-fold) and IFITM3 knock-out cells (510- and 500-fold) for PRVABC59, (purple bars)." (PMID 32370187, 2020). "In the case of IFITM, the four members (IFITM-1, IFITM-2, IFITM-3, and IFITM-5) are present in endosomes and lysosomes and have a critical role in the inhibition of viruses that require vesicles for effective infection." (PMID 32455136, 2020). "(C) HEK293T cells stably transfected with empty pQCXIP, IFITM3 WT-FLAG, or the indicated mutants were challenged with IAV PR8 strain (MOI of 0.1), fixed at 18 hr post-infection, stained with an anti-nucleoprotein antibody, and assessed by flow cytometry." (PMID 33112230, 2020). "Following infection with IAV A/Hong Kong/1/1968 (HK/1/68) for 24 h, most cells exhibited strong and clustered IFITM3 signals in the extranuclear space." (PMID 31212878, 2019). "Applying confocal and super-resolution imaging of endogenous IFITM3, we show that pre-existing IFITM3 clusters at early and late endosomal structures carry IAV at early time points of infection, prior to interferon induction." (PMID 31212878, 2019). "This study convincingly showed that Env mutations, which arise to evade autologous antibodies 6 months after infection, transform the IFITM3-resistant HIV-1 to an IFITM3-sensitive one." (PMID 30935048, 2019). "We therefore studied viral production effects driven by IFITM2 and IFITM3 with dual-tropic HIV-1 89.6, wherein cells were treated with the CXCR4 antagonist AMD3100 prior to and during infection." (PMID 30266929, 2018). "We noticed that infection by the dual tropic HIV-1 89.6 in U87.CD4.CCR5 cells was almost equivalently inhibited by IFITM1 and IFITM2; however, IFITM3 still exhibited the strongest inhibition among all three IFITMs." (PMID 30087232, 2018). "In agreement with the previous finding that IFITM3 preserves antiviral CD8 + T cells, individuals harboring rs34481144-A contained reduced numbers of these cells in lung airways during infection." (PMID 29162141, 2017). "Notably, high expression levels of goose IFITM3 were observed in respiratory tract tissues (lung and trachea), the target tissues of infection with influenza A viruses, compared to the other tissues, which might contribute to the inhibition of influenza A virus replication." (PMID 28386554, 2017). "TF strains are relatively resistant to IFITM-mediated restriction, yet matched viral clones derived 6 months following initial infection exhibited a gain of sensitivity to IFITM2 and IFITM3." (PMID 29162141, 2017). "Though requiring a higher MOI to see equivalent levels of infection, replication of SINV was also inhibited by IFITM3‐HA." (PMID 27219333, 2016).
infection (continued). "Considering that IFITM1 and IFITM3 regulate permeability of the cell membrane, it is plausible that SPTA1 is also involved in aiding the host cell’s architecture to impede infection." (PMID 29333229, 2016). "Infection by SFV fusion at the cell surface was inhibited by IFITM1, but was equally inhibited by IFITM3." (PMID 27219333, 2016). "Antiviral genes, including IFNA, IFNG, MX1, IFITM1, IFITM3, and IFITM5, were upregulated in response to infection." (PMID 25505077, 2015). "To confirm that the increased resistance of NEDD4 KO cells to influenza virus infection was due to increased levels of basal IFITM3, we knocked down IFITM3 in NEDD4 WT and KO cells for 24 hours prior to infection." (PMID 26263374, 2015). "The inhibitory effect of Δ21 IFITM3 on H3 and H7(FPV) infection was weaker than that of FL IFITM3 but still very prominent." (PMID 25314048, 2014). "IAV is a prototype pH-dependent virus, the entry and infection of which has been shown to be significantly restricted by IFITM proteins, particularly IFITM3, both in vitro and in vivo." (PMID 23358889, 2013). "Here, we show that IFITM3 mutants defective in target cell protection activity still markedly impair HIV-1 fusion/infection upon incorporating into virions, without affecting viral maturation or Env incorporation." (PMID 41897394, 2026). "Collectively, these findings imply that the influenza virus fuses with the limiting membrane of endosomes, but not with intraluminal vesicles, leading to productive infection, and that IFITM3 enrichment at these sites is critical for blocking viral fusion." (PMID 41879341, 2026). "Among them, we wanted to analyze the expression of interferon α and β, IFITM3, ISG15, MyD88, and IRF1 in DF-1 and DSK cells upon MVA infection and verify whether their expression is affected when STING functionality is impaired." (PMID 40981440, 2025). "At Day 14 of differentiation and Day 7 post-infection of cord blood CD34+ HSPC-derived megakaryocytes, IFITM3 expression levels were lower in infected cells relative to non-infected mature megakaryocytes, as assessed by both confocal microscopy and flow cytometry." (PMID 39354676, 2025). "Inhibition of autophagy after infection resulted in increased p62 levels and decreased Beclin-1, ATG7, and ATG5 levels, similar to the response to IFITM3 knockdown, whereas overexpression of IFITM3 had the opposite effect." (PMID 40681213, 2025). "This supports the notion that IFITM3 is especially important in emergent infections where there is an absence of pre-existing immunity." (PMID 40237465, 2025). "Although previous studies have identified certain polymorphisms in the ACE2, ADAM17, FURIN, IFITM3, and VDR genes associated with infection susceptibility to SARS-CoV-2, our findings did not reveal any such associations (data not shown)." (PMID 40296872, 2025). "In protection studies, both homologous and hetrosubtypic challenge infections were controlled, suggesting that B and T cell memory responses are functionally sufficient in the absence of IFITM3." (PMID 40501891, 2025). "Interferon-induced transmembrane protein 3 (IFITM3) and guanylate-binding proteins 1 and 4 (GBP1 and GBP4) show minimal expression in controls but are significantly upregulated in the moderate infection, indicating a strong antiviral response." (PMID 39928675, 2025). "The results showed that constitutive expression of IFITM3 in CD8+rather than CD4+TRM correlates with hypomethylation of the IFITM3 promoter 20 days after infection with influenza virus." (PMID 40895552, 2025). "Infection with C. parvum and knockdown of IFITM3 did not influence the number of HCT-8 cells, but increased the number of C. parvum." (PMID 40681213, 2025). "Meanwhile, the knockout of IFITM3 did not significantly affect the number of newly formed viral particles in the culture medium after infection of the cell lines." (PMID 38203797, 2024).
infection (continued). "We first examined single-cycle infections of these viruses in the absence of trypsin in control A549 cells versus those in which IFITM3 was depleted by shRNA knockdown." (PMID 39477971, 2024). "Myeloid dendritic cells in dormant infections also showed notable differences in mRNA expression, affecting neutrophil recruitment (C1QA, C1QB, ITGAM), immune checkpoint regulation (IFITM2, IFITM3, CST7, THBS1), and T-cell response (VISIG4, V-set immunoglobulin domain containing 4)." (PMID 39563367, 2024). "Another study investigating the RNA virus Sendai virus showed that IFITM3 does not limit infection and actually promotes the autophagic degradation of IRF3, limiting type I interferon responses." (PMID 39772131, 2024). "A mechanistic study revealed that IFITM3 expression is selectively maintained in the anti-influenza CD8+ resident memory T cells in the lungs so that these cells are resistant to IAV infection and capable of protecting against subsequent infections." (PMID 38793616, 2024). "Once again, infection by the human-, avian-, and swine-origin viruses was significantly potentiated in the human macrophages lacking IFITM3 with or without interferon treatment." (PMID 39477971, 2024). "By contrast, IFITM2 and IFITM3 did not inhibit but rather enhanced infection in agreement with previous studies." (PMID 36693093, 2023). "In the absence of infection in the four patients, it is conceivable that IFITM2 and IFITM3 are implicated in aseptic inflammation and cell detachment of PTCs." (PMID 38077419, 2023). "In a separate study, the overexpression of IFITM3 did not restrict but enhanced the spike-mediated infection in TMPRSS2-expressing cells, suggesting that altered usage of host protease or fusion at the plasma membrane subverts the effect of host IFITMs." (PMID 36992348, 2023). "We recently utilised a doxycycline (DOX)-inducible protein overexpression system in A549 airway epithelial cells to demonstrate that IFITM1, IFITM2, and IFITM3 are cellular host factors that inhibit IAV but not parainfluenza virus (PIV)-3 infection." (PMID 37111405, 2023). "Interestingly, IFITM3 was reported to restrict the entry mediated by the spike proteins of SARS-CoV, MERS-CoV, hCoV-229E, and hCoV-NL63, yet it enhances the infection of hCoV-OC43." (PMID 36423162, 2022). "In the case of LACV and ANDV, overexpression of any of the three IFTMs significantly suppressed infection, while only IFITM-2 and IFITM-3 could suppress infection by RVFV." (PMID 36298693, 2022). "A second surprising finding was that the infection rate of the HDV-1T strain was reduced only in HuH7-NTCP cells under IFITM3 knockdown conditions, but not in HepG2-NTCP cells, even if these cells showed reduced NTCP expression." (PMID 35458456, 2022). "To more visually reflect the effect of IFITM3 on PFV replication, we infected IFITM3 knockdown or control HT1080 cell lines with a PFV virus stock solution, and observed the state of the cells at different time points following infection." (PMID 36419065, 2022). "Indeed, when TMPRSS2 and IFITM3 were co-expressed in 293T-ACE2 cells, infection of SARS-CoV-2 S-pseudotyped viruses was less inhibited by IFITM3 compared to that in cells not expressing TMPRSS2." (PMID 36423162, 2022). "Viremic infection of other organs—such as the brain, liver, or kidneys—is not observed in IFITM3 KO mice, thus providing a severe infection model recapitulating the tissue-specific distribution of influenza virus dissemination." (PMID 35544568, 2022). "ISG12, IFITM3, Mx, and PKR were also slightly upregulated after infection." (PMID 36187980, 2022). "Similar to arenavirus GPpp infection, expression of IFITM3 alone did not affect MOPV replication or production." (PMID 35283811, 2022). "Based on this, it seems reasonable to suggest that an endosomal pH change under IFITM3 knockdown might affect the release of HBV and HDV from the endosome compartment and thereby also the infection rates." (PMID 35458456, 2022).
infection (continued). "Based on the MYTH and co-IP experiments performed in this study, this effect is proposed to rely on direct protein–protein interaction between IFITM3 and NTCP, even though more experiments are needed to establish at which stage of the infection process this PPI is critically involved." (PMID 35458456, 2022). "Although it was surprising that mislocalization of IFITM2 resulted in enhancement of infection rather than simply an absence of restriction, these data are consistent with a recent report suggesting that similar mutants of IFITM3 enhance SARS-CoV-2 infection." (PMID 33563656, 2021). "Likewise, the IAV-induced expression of IFITM3 polypeptide was further enhanced in NAA60-depleted cells by a significant 1.6-fold (P=0.022) and 1.7-fold (P=0.041) at 12 h and 24 h post-infection, respectively, compared to control cells." (PMID 35095845, 2021). "An enhancement of infection by all IFITMs was observed with MLV, significantly for IFITM3." (PMID 34933450, 2021). "In agreement with the results in IFITM1/2/3 knockout experiments and published results, IAV-LP infection was reduced by all IFITMs, most prominently by IFITM3, and infection of MLV-LP was not affected." (PMID 34933450, 2021). "IFITM3, initially upregulated on 2 dpi ANDV challenge and continued through 8–12 dpi, coinciding with peak viremia, is likely a cellular defense against ANDV infection." (PMID 34339406, 2021). "Given the higher susceptibility of KSHV than of RRV to bafilomycin A1, we speculate that a portion of RRV particles fuses at more peripheral sites, where infection is partially restricted by IFITM1 and IFITM3 Y20A and Δ1–21 mutants." (PMID 34933450, 2021). "Purified and normalized virions from IFITM3-overexpressing or control cells were inoculated to Marc-145-Vector or Marc-145-IFITM3-flag cells, and then the GFP-PRRSV positive cell percentage under different infection modes was analyzed using FACS at different time points." (PMID 32999030, 2020). "Clinically, AmphoB treatment might dramatically enhance the infection by SARS-CoVs and SL-CoVs, and overcome the IFITM3-mediated restriction." (PMID 32602823, 2020). "While the mechanisms by which IFITM3 can restrict HMPV/HRSV infection has not been fully elucidated, it is potentially similar to its action against IAV, whereby incoming virions are sequestered in endocytic compartments." (PMID 33276587, 2020). "IFITM2 and IFITM3 disrupted the early steps (entry and/or uncoating) of DENV and WNV infection." (PMID 32455136, 2020). "For example, IFITMs do not restrict infection of mouse leukemia virus, Machupo virus, Lassa virus, or lymphocytic choriomeningitis virus, highlighting the potential dual roles of IFITM3 in inhibiting viral replication." (PMID 32999030, 2020). "In this study, we further demonstrated that AmphoB treatment also efficiently attenuated the restriction of IFITM3 on the infection of SARSpp, MERSpp, NL63pp, 229Epp, and IAVpp, but not LASVpp." (PMID 32641482, 2020). "Interferon-induced transmembrane protein 3 (IFITM3) is downregulated during infection to evade antiviral restriction, although neither the viral mechanism of protein modulation, nor the cellular mechanism of VACV restriction by IFITM3, has been determined." (PMID 31067474, 2019). "Reovirus is the only non-enveloped virus whose infection and replication can be restricted by IFITM3." (PMID 31156602, 2019). "IFITM3 poses an important innate barrier against infection by several enveloped viruses and a non-enveloped virus." (PMID 31398796, 2019). "Although there were differences in induction of some ISGs (IFITM3, IRF3, ISG15, VIG1, and MX1), mRNA levels of type I IFNs were below the detection limit in pLNs or similar in spleens of B6 and CD169−/− mice post-FVC infection." (PMID 30595553, 2019). "We suggest that IFITM1, unlike IFITM2 and IFITM3, primarily functions through alteration of the plasma membrane and, as such, is able to restrict viruses at this initial point in infection." (PMID 30567988, 2019).